BRAF (B-Raf proto-oncogene, serine/threonine kinase)
Diseases named in the same sentence as BRAF in open-access papers (continued):
Sharing a sentence is not in itself a finding about the gene and the disease.
melanoma (continued). "Importantly, taking into account that vanicoside A and B could harm melanoma cell lines by the oxidative death mechanism, it could be supposed that they could also influence non-mutated cell lines (with the wild-type of the BRAF gene) which significantly expands their potential therapeutic range." (PMID 32610527, 2020). "Interestingly, it is also known that mutant BRAF, a common event on CMS1 tumors, regulates HIF-1α expression in melanoma, affecting cell survival under hypoxic conditions." (PMID 32231135, 2020). "Thus, we used the gene signature (n = 276 genes) characterizing the MITFlow/PTENneg melanomas and created a centroid that was applied on gene expression data derived from patients receiving ICB or BRAF/MEK inhibitors." (PMID 32245160, 2020). "In one case of malignant PEComa, BRAF and KIT mutations were found to be negative, with melanoma excluded." (PMID 33061792, 2020). "A closer look revealed that the essentiality of IGF1R was significantly higher in NRAS‐mutant cell lines compared with NRAS‐WT background and also generally in BRAF WT melanoma cell lines, which is mainly composed of NRAS and HRAS mutants, compared with the BRAF V600E mutants." (PMID 33073517, 2020). "Importantly, this striking effect on SOX10 protein levels was present in all melanoma cultures, irrespective of whether they harbor activating BRAF p.V600E, NRAS p.Q61K, or both mutations, and irrespective of whether they are sensitive to MAPK inhibition or resistant." (PMID 32238882, 2020). "Gender, BRAF status, Melanoma-molGPA, and concurrent TT/IT were not of prognostic significance for distant intracranial control." (PMID 32059731, 2020). "SIRT5 has been shown to be dispensable for BRAFV600E-mediated melanoma development and also does not affect sensitivity to a selective BRAF inhibitor." (PMID 33178616, 2020). "No concomitant mutation in BRAF and NRAS genes was detected, further confirming that deleterious mutations in these driver oncogenes are mutually exclusive in melanoma." (PMID 32751423, 2020). "About 10–20% of BRAF V 600-mutant melanoma patients have no response to any MEK1/2-ERK1/2 pathway inhibitors." (PMID 33392197, 2020). "The prognostic role of BRAF in melanoma progression is not as controversial as in lung cancer patients." (PMID 33260892, 2020). "Among all of the 112 acral melanomas, BRAF V600E was positive in 21 melanomas (18.8%) and negative in the remaining 91 (81.3%), as determined using IHC with a mouse monoclonal VE1 antibody (ab228461; Abcam, Cambridge, UK)." (PMID 32143442, 2020). "In a mouse model of melanoma, the concurrent treatment with CSF-1R inhibitor, PLX3397, and BRAF inhibitor, Vemurafenib, resulted in enhanced anti-tumor responses attributed to a significant reduction of tumor-infiltrating myeloid cells and an increase of tumor-infiltrating lymphocytes." (PMID 32656079, 2020). "Strikingly, even the combination of a BRAF and a MEK inhibitor, which is the new standard of care treatment in patients with BRAFV600E-mutated melanoma, did not alter SOX10 expressions levels." (PMID 32238882, 2020). "We found 23 of 25 cell lines and approximately 60% of melanoma biopsies expressed mGluR1 at both mRNA and protein levels, independent of the BRAF/NRAS genotypes." (PMID 33256089, 2020). "Additionally, platelet-derived growth factor receptor-beta (PDGFR-β), which is greatly increased in T-EVs discharged by melanoma cells resistant to the BRAF inhibitor PLX4720, can be transported to recipient melanoma cells." (PMID 33081785, 2020). "For example, BRAF-inhibitors alone work efficiently in BRAF-V600E-positive melanomas but not in BRAF-V600E-positive colon cancer." (PMID 32626653, 2020). "These functions were also observed in the context of BRAF inhibition, indicating that targeting BCL2L10 may enhance the clinical efficacy of other therapies against melanoma." (PMID 33396645, 2020).
melanoma (continued). "The comparison of the OS between the three groups of patients, i.e., (a) melanoma BRAF wild-type, (b) BRAF mutant (BRAFmut) treatment naïve and (c) pretreated with BRAF/MEKi (before ICI) melanoma showed a significantly better OS for patients in the first two groups (p = 0.01)." (PMID 32825510, 2020). "gained similar results upon downregulation of BRAF and AKT in melanoma cells." (PMID 33293661, 2020). "A combinação da terapia com inibidores BRAF e MEK é, no momento, a primeira escolha no melanoma metastático com a mutação BRAF, apresentando significativa melhora na sobrevida dos pacientes." (PMID 33295473, 2020). "Indeed, stromal fibroblasts in BRAF inhibitor treated tumours alter the ECM and produce a more regressive micro‐environment for melanoma cells." (PMID 31323160, 2020). "Clinical trials to date have demonstrated variable results with regard to efficacy, but BRAF/MEK-targeted therapy can be considered in patients with BRAF-mutant melanoma who do not respond to anti-PD1 therapy." (PMID 32645969, 2020). "Interestingly, intra-patient heterogeneity of BRAF and NRAS molecular alterations between paired primary melanoma and metastasis has been described with observed discordance rate 13,3%." (PMID 33100226, 2020). "It was shown in both melanoma and NSCLC that the concomitant BRAF inhibition with dabrafenib and inhibition of the downstream mitogen-activated protein kinase (MEK) with trametinib improved clinical response compared to BRAF inhibition alone." (PMID 33276639, 2020). "All BRAF variants in our study were identified in patients with lymph node metastasis, which support the later statement that BRAF is important in progression rather than initiation of the melanoma." (PMID 32083130, 2020). "In fact, NRP1 expression was basally very low in parental BRAF-addicted melanoma cells A375 and SK-MEL-28, and Gal-1 silencing did not significantly impact NRP1 levels." (PMID 32784465, 2020). "Furthermore, as the BRAF WT cohort of patients are a diverse group, treatment options are much less clear cut although immunotherapies, as with BRAFV600E melanoma are a promising albeit costly treatment approach." (PMID 32085796, 2020). "The combination of BRAF and MEK inhibitors is the most common melanoma targeted therapy." (PMID 32595510, 2020). "Although these are among the most recurrent mutations in melanoma and are associated with carcinogenesis, neither is a canonical UV signature mutation: NRAS Q61R is caused by a T>C mutation, while BRAF V600E is caused by a T>A mutation in a non-Dipyr context." (PMID 33207206, 2020). "Another example of the role of SOX10 in melanoma is the finding that ERK phosphorylates and regulates SOX10 sumoylation at lysine 55, which is required for the regulation of its transcriptional activity and target selection in BRAF-mutant melanoma." (PMID 33024276, 2020). "In addition, BRAF p.Val600Glu was also identified in CMN, suggesting that the alteration constitutes an early key somatic event in the transformation into melanoma." (PMID 32847629, 2020). "In line with the other results, Melanoma-associated mutations (BRAF, NRAS, c‐Kit) were absent and malignant melanoma was ruled out." (PMID 31309284, 2020). "Consistently, we found that dietary glutamine supplementation significantly reduced tumour growth in both melanoma PDX models independent of BRAF status." (PMID 32620791, 2020). "Moreover, nelfinavir is effective in BRAF and NRAS mutant melanoma cells isolated from patients progressed on MAPK inhibitor therapy and in BRAF/NRAS/PTEN mutant tumors." (PMID 33322354, 2020). "There is a growing body of evidence to suggest that mutations in neuroblastoma ras viral oncogene homolog (N-RAS) and v-raf murine sarcoma viral oncogene homolog B (BRAF), both activators of mitogen-activated protein kinase (MAPK-ERK), are involved in melanoma development." (PMID 32244473, 2020).
melanoma (continued). "Oncogenic BRAF and NRAS mutations are the most common melanoma driver mutations, yet these mutations typically do not match the UV signature." (PMID 33207206, 2020). "Experiments show that in the BRAF‐sensitive phase, peritumoral injection of the TLR7 ligand imiquimod preserves immunogenicity and delays resistance, thus representing a potentially effective novel therapeutic strategy for melanoma." (PMID 31702822, 2020). "Importantly, the study indicated that in a proportion of melanoma patients, USP28 was deleted, thereby functioning as a key biomarker for patients' response to the BRAF inhibitor therapy." (PMID 31938050, 2020). "Despite this, it has been demonstrated that some melanomas in stage III (rarely IV), having not been widely spread and carrying the BRAF mutation, can be treated surgically." (PMID 32013263, 2020). "It has also been shown that MEK and BRAF inhibitors can increase the number of macrophages, as well as their expression of tumor necrosis factor-α (TNF-α), mediating upregulation of MITF expression in melanoma cells through NF-κB activation." (PMID 33291749, 2020). "Administering BRAF inhibitors in the case of primary MAP3K8 overexpression further increases the expression of this protein, which in turn stimulates the proliferation of melanoma cells." (PMID 32605090, 2020). "There are no treatment options available for wildtype-BRAF/NRAS melanomas, which constitute ~30% of all CMMs." (PMID 32054078, 2020). "In contrast to BRAF mutations, NRAS-mutant melanomas are correlated with the nodular subtype and found in CSD skin." (PMID 32429485, 2020). "Data published in the Cancer Genome Atlas (TCGA) Network classify cutaneous melanomas into four genetic subgroups on the basis of the most frequently mutated genes involved in the mitogen-activated protein kinase (MAPK) pathway: BRAF, RAS (N-H-K), NF1, and triple wild-type (WT) melanomas." (PMID 33003469, 2020). "P124S is located in the MEK1 protein kinase domain and has previously been shown to confer resistance to BRAF- and MEK-inhibitor therapy in melanoma, but its role in EGFR-Ab resistance in CRC was unknown." (PMID 33322618, 2020). "New evidence demonstrates that BRAF and MEK inhibitors induce an increase in ROS in melanoma cells." (PMID 33091721, 2020). "Funnel plot analysis demonstrates no bias in published studies which analyse mutations in BRAF, NRAS, and KIT genes for patients with melanoma, according to their sex, melanoma subtype, localization of melanoma, chronic solar exposure, and ulceration." (PMID 31274706, 2020). "Genetic alterations in EGFR, ALK, ROS1, MET, HER2, KIT, BRAF, and germline BRCA1/BRCA2 have been shown to confer survival benefits on patients with certain solid tumors, including non-small cell lung cancer, breast cancer, and melanoma." (PMID 33194591, 2020). "It is documented that after 2 weeks of treatment with BRAF and MEK inhibitors, melanoma cells have been able to downregulate melanoma differentiation antigens (MDA) surface expression, decrease T cell activity, and surface display of increase immune checkpoint inhibitory receptors." (PMID 32092958, 2020). "This xenograft mouse model showed that HI-511 could suppress both vemurafenib-sensitive and -resistant melanoma growth through the inhibition of AURKB and BRAF V600E." (PMID 32863956, 2020). "The BRAF negative control (SKMEL103 melanoma cell line), besides empty droplets, presented a population only on the y-axis, being correctly classified as wild type." (PMID 33122747, 2020). "The Sal/4E1RCat combination had a minimal effect on the normal non-cancerous FF2441 fibroblast cell line, but statistically significantly decreased viability in melanoma cell lines containing mutant BRAF V600E and those lacking the mutant BRAF protein." (PMID 32637352, 2020).
melanoma (continued). "In addition to the positive correlations of CD68+ macrophages with iNOS+ cells and iNOS+ cells with BRAF status, we found that there were a significantly higher number of CD68+ macrophages in BRAF+ melanomas." (PMID 32843682, 2020). "Due to this role, ERK inhibitors may show promise as a method of overcoming the development of resistance and re-activation of BRAF and MEK in BRAFV600E melanoma." (PMID 32092958, 2020). "Therefore, combined treatment with BRAF and MEK inhibitors, which is the gold standard in malignant melanoma, was initiated." (PMID 33043759, 2020). "On the other hand, it is interesting to note that TERT promoter mutation is an independent prognostic marker in other cancers (e.g., melanoma, thyroid cancer, urothelial carcinoma) and is not influenced by other mutations such as RAS or BRAF mutations." (PMID 32957941, 2020). "Furthermore, glutamine transporter ASCT2 represents a potential therapeutic target for both BRAF wild type and BRAFV600E melanoma." (PMID 32528879, 2020). "MM314X is derived from a patient harbouring a BRAF-mutant melanoma not previously treated with BRAF and MEK inhibitors." (PMID 31857724, 2020). "Notably, the BRAF protein related to oncogenesis was also dose-dependently downregulated along with its downstream phosphorylated ERK1/2 proteins in BRAF-expressing A375 cells, indicating that FKB plays a critical role against oncogenesis in melanoma cells." (PMID 33053749, 2020). "In the studied population, most patients were more than 60 years of age, had an ECOG PS of 0 or 1, half had melanoma of the skin (mainly of the ALM subtype) and approximately three‐quarters had negative BRAF mutation status." (PMID 32515086, 2020). "Although the exact role of AEBP1 in CAFs in melanoma patients requires further analysis, Hu and colleagues conducted a detailed experiment to examine the potential role of AEBP1 in acquired drug resistance to BRAF inhibition of melanoma via NF-κB pathway." (PMID 32565808, 2020). "Taken together, we have identified a drug with anti-melanoma activity in vitro and in vivo that has the potential to be combined with the standard of care agent Vemurafenib and Cobimetinib in both BRAFV600E and BRAF WT melanoma." (PMID 32085796, 2020). "Accordingly, in this study we investigated the inhibitory effect of BEZ235 and selumetinib alone and in combination on BRAF mutant melanoma, colorectal and lung cancer cell lines with or without PI3K/Akt pathway mutations." (PMID 33081092, 2020). "Analysis of the TCGA cutaneous melanoma dataset also showed that methylation of the p16INK4a probe cg12840719 was higher in NRAS-mutant melanoma, compared to BRAF-mutant melanoma, although this was not statistically significant." (PMID 33076392, 2020). "An ongoing phase II study is currently investigating the efficacy of pembrolizumab (anti-PD-1 therapy) in combination with intermittent or continuous administration of BRAF and MEK inhibitors (dabrafenib and trametinib) in patients with advanced melanoma (NCT02625337)." (PMID 32260561, 2020). "An earlier study also detected CD4+ T cell responses to HLA class II-restricted epitopes from BRAF V600E in patients with BRAF V600E melanoma, although not in the context of clinical response after immunotherapy." (PMID 32117272, 2020). "Furthermore, afatinib and osimertinib have recently been approved for the treatment of EGFR mutated non-small cell lung cancers, while the combination of BRAF and MEK inhibitors improve overall survival in melanoma." (PMID 32087721, 2020). "On the contrary, treatment with Vemurafenib reduced the expression of p-p70S6k in control cells but not in cmMSC melanoma cells, confirming the resistance of A375-M6 cmMSC to the BRAF inhibitor." (PMID 32396749, 2020).
melanoma (continued). "In total, 547 patients were analyzed; 67.5% were 60 years old or more, 85.7% had an Eastern Cooperative Oncology Group performance status of 0–1, 50.3% had melanoma of the skin (mainly of the ALM subtype) and 73.5% had negative BRAF mutation status." (PMID 32515086, 2020). "As proof-of-concept, we have incorporated BRAF and histone deacetylase (HDAC) inhibitors into GON-BSA systems and validated the functionality of these devised assemblies as molecular weapons against human melanoma cells." (PMID 32266211, 2020). "Therefore, monotherapies using a BRAF inhibitor (BRAFi) or combination therapies of BRAF and MEK inhibitors (MAPKi) are now considered a mainstay of melanoma treatment." (PMID 31323160, 2020). "The development of BRAF inhibitors such as vemurafenib, dabrafenib, and encorafenib dramatically improved the overall response rate (ORR) and the overall survival (OS) in patients with this melanoma subtype." (PMID 33233603, 2020). "The hyperactivation of the RAS/RAF/MEK/ERK signaling pathway (hereafter MAPK), which is assessed in the vast majority of melanomas as a result of genetic alterations in BRAF, RAS, or NF1 among others, contributes to the pro-survival phenotype of melanoma cells." (PMID 32340261, 2020). "As RNA amounts extracted from EVs are limiting, the miRNomes of nEVs and hEVs were analysed by highly sensitive qPCR arrays for a BRAF mutant (A375) and for an NRAS mutant melanoma cell line (MelJuso), while analysis of the miRNomes of WCLs was performed by miRNA microarrays." (PMID 32183388, 2020). "There are currently only a handful of reports suggesting that BRAF and MEK inhibitors, or immune checkpoint inhibitors, may induce survival benefit in advanced melanoma patients with LM." (PMID 32947841, 2020). "Acetate dependence is specific to BRAF mutant but not NRAS mutant or wild-type BRAF/NRAS melanoma cells." (PMID 33121001, 2020). "We also examined a melanoma cell line A375MEK1Q56P, which exhibits resistance to BRAF inhibitors." (PMID 31462705, 2020). "In contrast, AXL inhibition in BRAF mutant melanoma may be more effective in PTEN wild-type patients, as phosphorylated AXL is only significantly increased in BRAF inhibitor-resistant cell lines in the context of endogenous PTEN." (PMID 33105713, 2020). "While the treatment of patients is currently based upon BRAF status and AJCC stage, routine germline testing may be incorporated into future iterations of the staging for melanoma to improve prognosis." (PMID 33077847, 2020). "The stark difference in the clinical activity of vemurafenib between BRAF mutant melanoma and BRAF mutant CRC was attributed to the complete lack of pathway reactivation in the former, principally related to absent or low level EGFR expression." (PMID 32922659, 2020). "There was a higher expression of BIM in BRAF-WT melanoma, compared to BRAF-MUT melanoma, although it is not statistically significant (Data not shown; Unpublished work)." (PMID 32764384, 2020). "Based on these data, today BRAF status is not considered a predictive factor for melanoma patients receiving immunotherapy." (PMID 31179334, 2019). "The primary clinical mechanism of acquired melanoma resistance to PLX4032 and other BRAF inhibitors (BRAFi) is the reactivation of MAPK pathway signaling which consequently leads to activation of dysregulated proliferation, aberrant cell cycle progression, and resistance to apoptosis." (PMID 30745871, 2019). "It appears that MEK inhibitors have some activity in BRAF-wt melanoma, but that this is not sustained." (PMID 30428063, 2019). "Moreover, the binding of endogenous BRAF with 14–3–3 proteins was attenuated after melanoma cells were treated with TNFα, which were shown to activate JNK/ITCH to facilitate BRAF ubiquitination." (PMID 31015455, 2019). "Vemurafenib received approval by the U.S. Food and Drug Administration in 2011 for the treatment of non-resectable BRAF mutant melanoma." (PMID 31416288, 2019).